CYP27B1 (cytochrome P450 family 27 subfamily B member 1)
Diseases named in the same sentence as CYP27B1 in open-access papers (continued):
Sharing a sentence is not in itself a finding about the gene and the disease.
parathyroid adenoma (1 paper, 2023). "CYP27B1 gene was analyzed for mutations correlated to parathyroid adenoma, as this gene encodes 25-hydroxy-vitamin D-1α-hydroxylase, a P450 mitochondrial enzyme, which converts 25-hydroxy-vitamin D to 1.25-dihydroxy-vitamin D, the functional form." (PMID 37223014, 2023). "No mutations were detected in the CYP27B1 gene, so its role in parathyroid adenoma pathogenesis was not confirmed." (PMID 37223014, 2023).
peritonitis (1 paper, 2014). Inflammation of the peritoneum (tissue that lines the abdominal wall and covers most of the organs in the abdomen). "This is endorsed by the increased expression of CYP27B1 and decreased expression of CYP24A1 in PD cells from peritonitis patients." (PMID 25549329, 2014). "PD cells from patients with peritonitis (n = 3) showed increased expression of CYP27B1 relative to PD cells from non-infected patients (4.97-fold higher±2.75, p<0.01)." (PMID 25549329, 2014).
prostate adenocarcinoma (1 paper, 2025). "In LNCaP prostate adenocarcinoma cells, treatment with 100 nM 25(OH)D3, alongside the CYP27B1 inhibitor genistein, resulted in a marked reduction in cell growth, suggesting that 25(OH)D3 can exert direct anti-proliferative effects." (PMID 40362248, 2025).
rectal cancer (1 paper, 2012). A primary or metastatic malignant neoplasm that affects the rectum. "Subsite-related differences in CYP27B1 expression were apparent to some extent in low-grade (G1 and G2) cancerous lesions as rectal cancers expressed almost twice as much CYP27B1 than tumors located in the proximal (p < 0.05) and distal colon (p < 0.01)." (PMID 24213465, 2012).
renal carcinoma (1 paper, 2015). A carcinoma arising from the epithelium of the renal parenchyma or the renal pelvis. "An upregulation of CYP27B1 mRNA reported in several studies on breast, renal cancers or squamous cell carcinoma requires an explanation." (PMID 25501638, 2015).
renal fibrosis (1 paper, 2020). A final common manifestation of a wide variety of chronic kidney diseases characterized by glomerulosclerosis and tubulointerstitial fibrosis. "ESA treatment also reduced renal fibrosis markers, as well as increased Cyp27b1 and reduced Cyp24a1 mRNA expression." (PMID 32476270, 2020).
schizophrenia (1 paper, 2022). A major psychotic disorder characterized by abnormalities in the perception or expression of reality. "We have also described over-expression of VDR, CYP27B1, and CYP24A1 in peripheral blood of patients with schizophrenia compared with healthy subjects in our previous study." (PMID 35279108, 2022).
seminoma (1 paper, 2023). A radiosensitive malignant germ cell tumor found in the testis (especially undescended), and extragonadal sites (anterior mediastinum and pineal gland). "Using TCGA mRNA expression of anabolic (CYP2R1, CYP27A1 and CYP27B1) and catabolic (CYP24A1) Vitamin D enzymes, positive (PTHLH, IFNG, and TNF) and negative (FGF23) feedback regulators could also clearly distinguish between pure seminomas and NSGCT." (PMID 37242266, 2023).
skin cancer (1 paper, 2021). "The skin provides the best examples in that hair follicle cycling requires the VDR but not 1,25(OH)2D, and chemical‐ and UVB‐induced skin cancer occur in the Vdr null mouse but not in the Cyp27b1 null mouse." (PMID 34950833, 2021).
Systemic Lupus Erythematosus Disease (1 paper, 2022). "The mRNA expression of CYP27B1 negatively correlated with the Systemic Lupus Erythematosus Disease Activity Index (r = −0.331, p = 0.003)." (PMID 36326421, 2022).
thyroid autoimmunity (1 paper, 2015). "Recently, several genetic studies have demonstrated an association between thyroid autoimmunity susceptibility and gene polymorphisms of numerous proteins and enzymes that are associated with vitD functions, including VDR, DBP, CYP27B1, and CYP2R1." (PMID 26681939, 2015).
urothelial bladder cancers (1 paper, 2015). "In summary, VDR and CYP27B1 expression was down-regulated in urothelial bladder cancers in comparison to normal tissue." (PMID 26501255, 2015). "CYP27B1 expression was found both in cytoplasm of all normal epithelial cells and in 65 of 71 samples of urothelial bladder cancers (91.5%)." (PMID 26501255, 2015). "In conclusion, expression of the VDR and CYP27B1 are deregulated in urothelial bladder cancers." (PMID 26501255, 2015). "Therefore, the aim of this study was to evaluate the relationship between expression of the VDR and CYP27B1 and prognostic markers (such as tumor advancement, presence of metastases, tumor grade, mitotic activity, non-classic differentiation) in urothelial bladder cancer and its clinical outcome." (PMID 26501255, 2015).
uveal melanoma (1 paper, 2019). A melanoma derived from melanocytes of the uveal tract. "In uveal melanoma, the values of CYP27B1 labelling were significantly lower than in normal melanocytes and other uveal cells (the Wilcoxon signed-rank test, p < 0.001)." (PMID 31235702, 2019). "The levels of VDR, CYP24A1, CYP27B1 and RORs were always the lowest in the cells of uveal melanoma and higher in normal uveal melanocytes and other normal uveal cells." (PMID 31235702, 2019). "The levels of VDRn and VDRa increased together with those of the CYP27B1 value (Spearman’s rank correlation, rho = 0.401, p = 0.028 and rho = 0.390, p = 0.033, respectively) in uveal melanoma cells." (PMID 31235702, 2019). "This is significant because until now there has been no paper published, that would describe presence of VDR, hydroxylases CYP27B1 and CYP24A1, and RORα and RORγ in the human uveal tract and uveal melanomas." (PMID 31235702, 2019). "To fill the gap in our knowledge on vitamin D activity in uveal melanoma, we decided to evaluate the expression pattern of the VDR, CYP27B1 and CYP24A1 hydroxylases and RORα and RORγ in the cells of uveal melanoma, in normal melanocytes and in other normal uveal cells in humans." (PMID 31235702, 2019).
X-linked hypophosphatemia (1 paper, 2025). X-linked hypophosphatemia (XLH) is a hereditary renal phosphate-wasting disorder characterized by hypophosphatemia, rickets and/or osteomalacia, and diminished growth. "Genetic testing via the Renasight panel was negative for pathogenic mutations, including those associated with X-linked hypophosphatemia (XLH), and whole-exome sequencing revealed no CYP27B1 mutations." (PMID 40951211, 2025).
cancer (49 papers, 2010 to 2025). A tumor composed of atypical neoplastic, often pleomorphic cells that invade other tissues. "The relationship between polymorphisms in CYP27B1 and cancer susceptibility has been extensively studied, although the results have been inconsistent." (PMID 40630116, 2025). "This case‐control study of 693 newly‐diagnosed BC cases and 714 cancer‐free controls evaluated the effect of multiple exposures to environmental factors and polymorphisms in CYP27B1 and IL‐13 on BC risk." (PMID 31041852, 2019). "To better explore the precise relationship, we performed a meta-analysis and trial sequential analysis (TSA) to characterize the associations of GC (rs4588 and rs7041) and CYP27B1 (rs4646537, rs3782130) polymorphisms with cancer susceptibility." (PMID 31467173, 2019). "Relationships between CYP27B1 and GC polymorphisms and cancer susceptibility have been widely investigated, whereas the results are inconsistent." (PMID 31467173, 2019). "Associations between CYP27B1 and GC polymorphisms and cancer risks were examined, and additional large samples are necessary to validate our results." (PMID 31467173, 2019). "Besides polymorphisms, expression level of CYP27B1 has potential implications in the prognosis for a variety of cancers." (PMID 40630116, 2025). "We strictly searched EMBASE, PubMed, Web of Science, WanFang and CNKI electronic databases for relevant studies exploring the associations of GC (rs4588 and rs7041) and CYP27B1 (rs4646537, rs3782130) polymorphisms with cancer risks according to search strategy." (PMID 31467173, 2019). "CYP27B1, though majorly present in the kidney is also found to expressed in several extrarenal sites such as cancer cells, which suggests the role of dietary vitamin D in cancer therapy." (PMID 39618688, 2024). "When K = 2, each detected gene set, except for (CDKN2A, CYP27B1) identified by method iMCMC, is enriched in one cancer-related biological pathway." (PMID 37221474, 2023). "High serum 25(OH)D has been found to be protective against cancer, only when 25(OH)D 1-α hydroxylase (CYP27B1) (converts serum 25(OH)D to 1,25(OH)2D) activity is optimum." (PMID 35743729, 2022). "CYP27B1, the vitamin D metabolizing enzyme, was upregulated at the beginning of the cancer carcinogenesis process with an increased expression of the vitamin D receptor." (PMID 35127477, 2021). "The molecular mechanisms responsible for reduced CYP27B1 expression in the process of cancer progression are still not fully understood." (PMID 34208589, 2021). "It should also be underlined that many types of cancer cells present alterations in vitamin D metabolism and action as a result of Vitamin D Receptor (VDR) and CYP27B1 expression dysregulation." (PMID 34208589, 2021). "The expression of CYP27B1 in cancers also showed a similar trend giving a plausible explanation for the overexpression of VDR in cancer." (PMID 32679655, 2020). "Increased level of CYP27B1 expression is characteristic for the initial stage of malignant tumors, acting as an inhibitor of the progression of the disease." (PMID 32197412, 2020). "CYP27B1 and group-specific component (GC), the main enzyme responsible for the degradation and transport of active vitamin D, play important role in many cancer-related cellular processes." (PMID 31467173, 2019). "In some cancers, such as parathyroid carcinomas, the expression levels and activity of CYP27B1 in the cancer cells are lower than in normal cells." (PMID 30216977, 2018). "Recently, the extra-renal expression of CYP27B1 has been identified and in vitro conversion of 25(OH)D to 1α,25(OH)2D3 has been found in some cancer cells with CYP27B1 expression." (PMID 27529229, 2016). "CYP27B1 expression was lower in cancer cells than in normal epithelial cells (p = 0.03 with Mann–Whitney U test), but its expression did not correlate with tumor stage (pT), metastasizing, grade, mitotic activity or overall survival." (PMID 26501255, 2015).
cancer (continued). "In tumors classified according to grade in whole cancer material, there were statistically significant differences in CYP27B1 levels only between G1 and G3 tumors." (PMID 25501638, 2015). "VDR and CYP27B1 expression in mammary adipocytes also contribute to the anti-cancer effects in the whole tissue, since in response to 25(OH)D adipocytes secrete diffusible signals that inhibit morphogenesis of the adjacent ductal epithelium." (PMID 24982636, 2014). "Data from 105 cancer patients on CYP27B1, VDR, CYP24A1, and COX-2 mRNA expression in relation to tumor grade, anatomical location, gender and age were fit into a multivariate model of exploratory factor analysis." (PMID 24213465, 2012). "CYP27B1 has been found to activate vitamin D, which protects against cancer." (PMID 38672780, 2024). "In addition, when activated by CYP27B1, calcitriol can mediate the arrest of multiple cancer cell cycles." (PMID 35990259, 2022). "Furthermore, we evaluated the association of CYP27B1 rs4646536 and CYP2R1 rs12794714 and rs10766196 polymorphisms with CRC risk in a total of 490 subjects, including 245 CRC patients and 245 non‐cancer controls." (PMID 33058307, 2021). "It was observed that CYP27B1 expression is inversely correlated with the progression of tumors of prostate, lung, parathyroid, colon and skin, suggesting that local production of 1,25(OH)2D3 in CYP27B1-expressed tissues could be crucial for cancer prevention." (PMID 34208589, 2021). "Additionally, the expression of CYP27B1 in alveolar macrophages from lung cancer patients presented a positive correlation with cancer progression." (PMID 34208589, 2021). "Furthermore, decreased levels of CYP27B1 expression in cancer patients demonstrated the importance of vitamin D’s autocrine/paracrine function in maintaining normal proliferation and differentiation of local tissues." (PMID 32847594, 2020). "Additionally, CYP27B1 is expressed in many cancers, often at higher levels than in the surrounding normal tissue." (PMID 30321335, 2019). "Most cancers express not only the VDR but also CYP27B1 and CYP24A1 thus allowing cancer cells to regulate locally 1,25(OH)2D levels, and it has been reported that cancers expressing CYP27B1 tend to be well differentiated while cancers which do not express CYP27B1 tend to be poorly differentiated." (PMID 29951549, 2018). "Given that CYP24A1 is an enzyme that degrades calcidiol and calcitriol, it is likely that cancer cells may upregulate CYP24A1 expression to reduce local concentrations of calcitriol, which is similar to the reduction of CYP27B1 in some cancers." (PMID 29657326, 2018). "25(OH)D has therefore emerged as a promising regimen to treat cancers with CYP27B1 expression." (PMID 27529229, 2016). "Similarly, disturbances of the expression of the VDR and enzymes regulating vitamin D activation (CYP27B1) and metabolism (CYP24A1) are linked to the aggressiveness and outcomes of some malignant tumors." (PMID 26501255, 2015). "Renal diseases can affect vitamin D activation, since the second step of vitamin D hydroxylation catalyzed by CYP27B1 takes place in kidney cells and could decrease the usefulness vitamin D supplementation in cancer patients." (PMID 26501255, 2015). "CYP27B1 expression was significantly higher in the normal epithelium than in cancer cells." (PMID 26501255, 2015). "However, in cancers classified according to tumor grade in the analyzed section, a gradual decrease in CYP27B1 was observed with increasing tumor grade, and a strong negative correlation with CYP27B1 immunostaining was found (r=−0.4206, p=0.0002)." (PMID 25501638, 2015). "Increased expression of CYP27B1 in cancer tissues may convey some chemoprevention to these cancers due to increased conversion of 25(OH)D3 of 1,25(OH)2D3." (PMID 26260259, 2015). "Moreover, within tumor compartments with higher proliferative activity and newly invading cancer cells, CYP27B1 expression was clearly decreased." (PMID 25501638, 2015).
cancer (continued). "Likewise, CYP27B1 was differentially expressed within borders and central parts of the cancer with significantly stronger CYP27B1 expression in older tumor compartments." (PMID 25501638, 2015). "Of those, 28 (45.9%) cancers showed low and 21 (34.4%) showed medium CYP27B1 levels." (PMID 25501638, 2015). "This may suggest that local activation of vitamin D3 by CYP27B1 can influence an immune response against cancer cells." (PMID 25501638, 2015). "Taken together, CYP27B1 is a biomolecule that may constitute a potential target in cancer therapy." (PMID 34208589, 2021). "Besides, CYP27B1 may weaken the anticancer functions by locally altering the catabolic and anabolic progress of active vitamin D in cancer." (PMID 35127477, 2021). "Furthermore, decreased CYP27B1 expression in cancer cells is related to a poorer clinical outcome." (PMID 33227893, 2020). "However, to date, there is no systematic evaluation on how CYP27B1 and GC polymorphisms are involved in development of cancers." (PMID 31467173, 2019). "However, the molecular mechanisms responsible for the progressive reduction of CYP27B1 expression during cancer progression are largely unknown." (PMID 29657326, 2018). "Given that normal mammary cells utilize 25(OH)D3 as substrate for local tissue generation of 1,25(OH)2D3, imbalanced expression of either CYP24A1 or CYP27B1 favoring catabolism could theoretically contribute to escape of developing tumor cells from anti-cancer VDR signaling." (PMID 24982636, 2014). "It was also reported that increased regulation of the vitamin D synthesis gene CYP2R1 and CYP27B1 and vitamin D metabolic genes CYP24A1 leading to changes in vitamin D bioavailability and anti-tumor activity, then influence the development of cancer." (PMID 37644572, 2023). "On the one hand, cancer cells present disturbances in expression of VDR and CYP27B1 that lead to disorders of vitamin D metabolism and action." (PMID 34208589, 2021). "During tumor progression elevated CYP27B1 remains constant, whereas COX-2 peaks in low grade and CYP24A1 in high grade cancers." (PMID 24213465, 2012). "Data regarding the expression of CYP27B1 in cancers are not univocal and dependent on several factors, including type of cancer and grade." (PMID 35741675, 2022). "Furthermore, it would be interesting to analyse the expression of CYP27B1 and its interactions with VDR and CYP24A1 in cancer cells." (PMID 36362766, 2022). "CYP2R1 and CYP27B1 are dysregulated in different types of cancer, but the mechanism behind the dysregulation is not clearly defined." (PMID 33058307, 2021). "However, in many type of cancer cells this VDR and CYP27B1-mediated regulation is disturbed which leads to disorders of vitamin D metabolism and action." (PMID 34208589, 2021). "Although, the molecular mechanisms that regulate CYP27B1 expression in particular types of cancer are not fully recognized." (PMID 34208589, 2021). "A recent study in mice with genetic absence of Cyp27b1 kept on a rescue diet to maintain normal calcium homeostasis for 1 year demonstrated a higher incidence of a variety of cancers compared with wild-type mice or null mice treated with 1,25(OH)2D." (PMID 30321335, 2019). "Subsequent analysis revealed statistically significant differences in the percentage of Ki67-positive cancer cells between regions without CYP27B1 expression and compartments with low and medium CYP27B1 expression." (PMID 25501638, 2015). "Activities of the enzymes that degrade (CYP24A1) and activate vitamin D (CYP27B1) were suppressed in MCSCs, but not in cancer cells propagated under high attachment conditions." (PMID 23341935, 2013). "Moreover, given the observed decline in the expression of CYP27B1, VDR, CYP11A1, and RORα/γ during cancer progression, as previously discussed, the utility of VD-based treatments may be confined to early rather than advanced stages of the disease." (PMID 38689243, 2024).
cancer (continued). "The study of 25(OH)D levels and the correlation with the level of cancer mortality may not reflect the real situation in the prostate, because it is CYP27B1 that determines the bioavailability of the active metabolite of vitamin D." (PMID 32197412, 2020). "Potentially the interaction between the variants in CASR and in the CYP27B1 genotypes, which activates the ligand for the CASR promoter, could contribute to the etiology of cancer, however this has not been demonstrated yet." (PMID 32197412, 2020). "Additionally, because the expression levels of CYP27B1, VDR, CYP11A1, and RORα/γ in cancer cells progressively decline during cancer progression the effectiveness of vitamin D-based therapy may be limited to only early stages, but not late stages, of cancer." (PMID 29657326, 2018). "Additionally, it has been shown that the expression of mRNA for CYP27B1 and the VDR was higher in carcinomas versus non-neoplastic tissue." (PMID 20831823, 2010).